AXL (AXL receptor tyrosine kinase)
Diseases named in the same sentence as AXL in open-access papers (continued):
Sharing a sentence is not in itself a finding about the gene and the disease.
cancer (continued). "The binding of antibody part of BA3011 to AXL initiates intracellular translocation of antibody-drug conjugate (ADC) complex followed by the release of MMAE ultimately leading to cancer cell death." (PMID 37469409, 2023). "The TAM (TYRO3, AXL, MerTK) subfamily is prominent in multiple cancer types resistant to various therapeutic agents, such as targeted and conventional chemotherapy." (PMID 37116196, 2023). "Activated EGFR pathways and downstream MEK/ERK signaling were reported to promote AXL mRNA expression through the JUN transcription factor in a number of cancer cells." (PMID 37047640, 2023). "GAS6–AXL signaling is crucial for cancer progression and metastasis in several types of cancers AXL can be activated in both GAS6–dependent and –independent manners." (PMID 37834326, 2023). "AXL is overexpressed in many types of cancer, including NSCLC, breast, gastric, colorectal, and prostate cancer." (PMID 36902280, 2023). "Mechanistically, we demonstrated that AXL, an emerging target for cancer therapy, was a novel protein substrate of GALNT2 and GALNT2 regulated AXL degradation primarily through the proteasome‐dependent pathway." (PMID 36409270, 2023). "Here, the authors identify CNK2 as a key mediator of cancer cell motility, linking extracellular stimuli via AXL signalling and downstream activation of ARF6 GTPase, resulting in increased metastasis in preclinical models." (PMID 37322019, 2023). "BGB324 (R428, bemcentinib) is a highly potent new anti-cancer compound that blocks AXL autophosphorylation, leading to inhibition of cancer cell proliferation, invasion and metastasis." (PMID 35332208, 2022). "In many other cancer types, AXL signaling is a common resistance mechanism to targeted therapies, including ERK/MEK inhibitors, BRAF inhibitors, imatinib, sunitinib, WEE1 inhibitors, or lapatinib." (PMID 35572601, 2022). "For the first time to our knowledge, we provide experimental evidence for the existence of a ROBO3/AXL/p-STAT3 regulatory axis in cancer." (PMID 35993361, 2022). "Neutrophil-derived Gas6 then activates the receptor tyrosine kinase AXL on metastatic cancer cells and promotes metastatic growth in the liver." (PMID 35022267, 2022). "An emerging function of AXL during cancer progression is its role in the plastic and dynamic program called epithelial-to-mesenchymal transition (EMT)." (PMID 35158733, 2022). "In the present study, we investigated the expression of AXL in PTC cancer tissue and control tissue via immunohistochemical staining." (PMID 36203174, 2022). "Together, these studies have led to a better understanding of the mechanisms linking AXL, immune evasion, and immunogenicity in cancer." (PMID 35572601, 2022). "In human cell lines, AXL expression seems to be restricted to invasive and mesenchymal lines, raising the possibility that AXL is a marker for mesenchymal cancers, like TNBC." (PMID 35158733, 2022). "AXL has also been linked to epithelial-to-mesenchymal transition (EMT)-like phenotype and acquired resistance to both conventional and targeted anti-cancer therapies." (PMID 35622156, 2022). "Signals downstream of AXL advantage cancer cells throughout the metastatic process and lead to therapy resistance." (PMID 35158733, 2022). "Those fibroblasts subsequently promoted a switch toward a more epithelial state, reducing AXL levels and promoting proliferation of cancer cells leading to the formation of macrometastasis." (PMID 35158733, 2022). "YES-associated protein 1 (YAP1) is another key co-transcriptional regulator of AXL in various cancer systems." (PMID 35572601, 2022). "Several biological triggers within the tumors that are known to promote metastasis, such as TGF-β/EMT and hypoxia, impact AXL expression levels in cancer cells." (PMID 35158733, 2022). "The expression levels of AXL in PTC cancer tissue were analysed using immunohistochemistry (IHC) staining." (PMID 36203174, 2022).
cancer (continued). "AXL was found to be essential for cancer cell hypoxia-induced EMT, invasion and cytokine production." (PMID 35158733, 2022). "In support of this role, AXL has been found to be upregulated in chemo-resistant cells in a variety of cancers." (PMID 35158733, 2022). "Before we can apply AXL-targeting therapeutic strategies to their full potential in cancer treatment, it is important to better understand the consequences of effective, systemic AXL inhibition." (PMID 35158733, 2022). "Specifically examining the role of Axl in TNBC, in a study conducted in 2016, treatment with an anti-AXL monoclonal antibody inhibited in vitro metastasis of AXL-positive cancer cells." (PMID 35158750, 2022). "Several AXL small molecule inhibitors, AXL antibodies for cancer therapy, and soluble decoy receptor molecules have been tested in clinical trials." (PMID 36551940, 2022). "Mudduluru and colleagues identified a GC-rich region (-556 to +7) containing specificity protein (SP)-binding sites sufficient to regulate basal AXL promoter activity in multiple cancer cell lines." (PMID 35572601, 2022). "As expected, warfarin treatment abolished the previously observed increase in AXL activation (pAXL) in cancer cells in the gemcitabine treated cohort and cancer cell proliferation (Ki67+) rates were reduced, while neutrophil numbers remained unchanged." (PMID 35022267, 2022). "For example, while a combination of radiation therapy and checkpoint immunotherapy have been suggested to treat various cancers, tumors resistant to this strategy have been shown to overexpress AXL." (PMID 35158733, 2022). "More recently, an original approach exploited AXL as a cancer antigen for chimeric antigen receptor (CAR)-T cell therapy." (PMID 35158733, 2022). "Many laboratory studies have shown that the GAS6/AXL axis promotes cell invasion, proliferation and survival, thus contributing to cancer progression and metastasis." (PMID 35158733, 2022). "Various approaches to inhibit AXL have been studied for cancer treatments including small molecule inhibitors that compete with ATP-binding or monoclonal antibodies." (PMID 35158733, 2022). "A body of work now suggests that inhibition of AXL, and in some cases TAMs more generally, leads to an antitumorigenic microenvironment by affecting angiogenesis and immune response at the cancer and stromal cells levels." (PMID 35158733, 2022). "The AXL/GAS6 axis is required for the activation of hepatic stellate cells (HSC) that can promote a permissive environment for cancer development by the production of extracellular matrix and inflammation." (PMID 35158733, 2022). "In conclusion, numerous lines of investigation identify AXL as a strong therapeutic target with the aim to enhance the efficacy of cancer treatments." (PMID 35158733, 2022). "We demonstrated that AXL expression sensitizes cancer cells to the suppressive effect of metformin on cell survival, leading to apoptosis." (PMID 35936716, 2022). "In sum, the data published so far point to a critical role for AXL in mediating normal and cancer cell plasticity in various contexts." (PMID 35572601, 2022). "In the bone marrow niche, osteoblasts produce GAS6 that can activate AXL on the surface of nearby disseminated cancer cells." (PMID 35158733, 2022). "Accordingly, the next sections will discuss our current understanding of AXL function in a variety of cancer-related biological processes that are both intrinsic and extrinsic to cancer cells." (PMID 35158733, 2022). "AXL, a TAM receptor tyrosine kinase (RTK), and its ligand growth arrest-specific 6 (GAS6) are implicated in cancer metastasis and drug resistance, and cellular entry of viruses." (PMID 35622156, 2022). "MicroRNAs such as miR-199a/b, miR-7, and miR-34a, as well as long non-coding RNAs, have been reported to negatively regulate AXL translation in cancer cell lines." (PMID 35572601, 2022).
cancer (continued). "Altogether, these results suggest that the persistence of AXL expression and signaling in disseminated cancer cells can lead to dormancy in the metastatic niche in some cancers." (PMID 35158733, 2022). "Among the cancer clones displaying mesenchymal phenotypes, those with high AXL expression exhibited pronounced intrinsic resistance to NK and CTL-mediated lysis." (PMID 35572601, 2022). "AXL has been implicated in many steps of the metastatic cascade and recent studies have clarified the cancer cell-intrinsic AXL contributions to this complex process." (PMID 35158733, 2022). "Our results indicate that AXL-dependent high basal cellular ROS levels enhance autophagy through activation of AMPK-ULK1 signaling in cancer cells in response to metabolic stress." (PMID 35936716, 2022). "In the present study, to validate our conjecture, immunohistochemical staining was used to detect the expression levels of integrin β3 and AXL in cancer biopsy samples before erlotinib treatment and after acquired erlotinib resistance in patients with NSCLC." (PMID 35805163, 2022). "Increased AXL expression has been shown to correlate with decreased patients’ survival and metastasis of cancer cells in a plethora of solid cancers." (PMID 35158733, 2022). "In this review, we describe how AXL contributes to metastatic progression by governing various biological processes in cancer cells and in stromal cells, highlighting the potential of its inhibition." (PMID 35158733, 2022). "The receptor tyrosine kinase AXL has been implicated in EMT, invasion and chemo-resistance of several human cancers." (PMID 35303925, 2022). "AXL is a promising cancer target because it is expressed in many solid tumor types and is weakly expressed in normal tissues." (PMID 36551940, 2022). "AXL is required at multiple steps of the metastatic cascade where its activation in cancer cells leads to EMT, invasion, survival, proliferation and therapy resistance." (PMID 35158733, 2022). "Altered expression of AXL in cancer has been studied as a mechanism of acquired resistance to cetuximab and targeting of AXL has been shown to resensitize cells and tumors to EGFR-targeted therapy." (PMID 35461210, 2022). "AXL has also been reported to drive the expression of the immune checkpoint protein PD-L1 on cancer cells via the PI3K-AKT axis to prevent T-cell activation." (PMID 35158733, 2022). "Targeting AXL overcomes acquired resistance to osimertinib and other EGFR-TKIs38,39, and multiple AXL inhibitors have been developed and advanced to clinical trials involving cancer therapy to overcome drug resistance." (PMID 35643725, 2022). "IHC analysis also confirmed a decrease in Tregs in both carcinomas, in both upfront add-on therapy and maintenance add-on of the AXL inhibitor." (PMID 35356198, 2022). "Given the role of AXL in the development, progression, and drug resistance of cancer, AXL holds great promise as a predictive biomarker and therapeutic target." (PMID 34926461, 2021). "AXL is instrumental in controlling genetic programs of epithelial-mesenchymal and mesenchymal-epithelial transitions, enabling cancer cells to metastasize." (PMID 34638349, 2021). "Cancer cells use the AXL pathway to detect toxic environments and to activate molecular mechanisms, thereby ensuring their survival or escape from the toxic zone." (PMID 34638349, 2021). "The targeting of AXL moves cancer cells toward the epithelial end of EMT/MET spectrum and sensitizes them to chemo-, radio- or targeted therapies, which efficiently eradicate proliferating epithelial cells." (PMID 34638349, 2021). "The AXL protein plays an important role in promoting cancer development, such as proliferation, migration, invasion and survival of cancer cells." (PMID 34439388, 2021). "Aberrant expression of AXL promotes phenotypes associated with EMT and metastasis, and inhibition of AXL reduces indicators of EMT/metastasis in various cancers." (PMID 34830794, 2021).
cancer (continued). "In another study, it was shown that GAS6 and AXL (from cancer cells) are required for TGFβ2-mediated cell growth suppression in PCa, where AXL positively regulates the expression of TGFβ and TGFβ receptor 2 (TGFβR2)." (PMID 34208521, 2021). "In this study, we used mass spectrometry-based proteomics to quantify the cancer signaling regulated by AXL activation." (PMID 34439388, 2021). "Targeting AXL for cancer treatment is under the spotlight, and several clinical studies involving the use of anti-AXL have been conducted." (PMID 34778071, 2021). "The findings emphasize that AXL bypass track is employed by chemoresistant cancer cells upon EGFR inhibition to enter a persister state and evolve resistance to EGFR-TKIs." (PMID 33850249, 2021). "Activation of AXL signaling has an immunosuppressive role to reduce the antitumor immune response and help cancer cells avoid host immune surveillance." (PMID 34439388, 2021). "KRIBB11 effectively decreased the HSP70/BAG3/BCL2 and EGFR/MET/AXL proteins, leading to apoptosis of resistant cancer cells." (PMID 34203709, 2021). "Previous reports that addressed the effects of AXL inactivation in different cancer cell models were based on knock-down by RNA interference or kinase activity inhibition by different small chemicals." (PMID 34948046, 2021). "MER and AXL are proto-oncogenes, and their aberrant expression in various cancers has been reported to contribute to cancer metastasis, growth and drug resistance." (PMID 34721022, 2021). "In later stages of the metastatic process, the downregulation of AXL signaling was required for the interaction between cancer cells and the microenvironment in the metastatic niches, and successful metastatic colonization of the lungs." (PMID 34638349, 2021). "Despite the important role of AXL in cancer development, a deep and quantitative mapping of its temporal dynamic signaling transduction has not yet been reported." (PMID 34439388, 2021). "The involvement of AXL in the relapse and metastasis of treatment-treated cancer tumors came as a surprise to us." (PMID 33850249, 2021). "Further, via the ABL2 protein intermediate, AXL can also act upstream of TAZ in some cancer types to promote a feed-forward activation loop amenable to therapeutic intervention." (PMID 33408328, 2021). "NCI-H820 cancer cells express an EGFR drug-sensitive mutation (an exon 19 deletion), an EGFR drug-resistance mutation (T790M), activated AXL, and MET amplification, conferring resistance to erlotinib, gefitinib, and afatinib." (PMID 34203709, 2021). "AXL receptor tyrosine kinase mediates multi-drug resistance in cancer cells and supresses tumor immunity." (PMID 34263254, 2021). "AXL inactivation occurs, either by the inhibitors or through RNA interference sensitized cancer cells to gamma-irradiation, antimitotic, and DNA damaging compounds in vitro." (PMID 34638349, 2021). "AXL inhibition in various mouse cancer models reduced metastatic spread and improved the survival of the animals." (PMID 34638349, 2021). "Another feature that specifies a broad role of AXL pathway in cancer biology is the incorporation of AXL in oncogenic signaling pathways operating in various cancers." (PMID 34638349, 2021). "Based on previous studies associating the induction of AXL expression during EMT in cancer cells and reported studies on some HCC cell lines, we decided to compare the relative expression of AXL in a large panel of HCC cell lines." (PMID 34948046, 2021). "Our study identified more than 1000 phosphotyrosine sites and discovered that activation of AXL can upregulate multiple cancer-promoting and cell migration/invasion-related signaling pathways." (PMID 34439388, 2021). "Of note, our in vitro studies indicated that the concentration of 5-Aza-dC to which AXL-positive cells are sensitive are well within the 5-Aza-dC blood concentrations observed in clinical trials for the treatment of different cancer types." (PMID 34254585, 2021).
cancer (continued). "AXL receptor tyrosine kinase (AXL) and receptor tyrosine kinase like orphan receptor 2 (ROR2) are cancer-associated antigens." (PMID 33482842, 2021). "Accumulating evidence had presented that AXL expression was correlated with poor prognosis or metastasis in various cancer types." (PMID 34838035, 2021). "A subpopulation of AXL-positive cancer cells were found in erlotinib-naïve tumors, providing rationale to treat mtEGFR-expressing NSCLCs with AXL and EGFR TKIs combined in order to delay or prevent resistance." (PMID 34830794, 2021). "High levels of AXL transcript were also observed in M/MSL TNBC cell lines of the Cancer Cell Line Encyclopedia (CCLE)." (PMID 33785524, 2021). "For example, CAFs enhanced oral squamous cell carcinoma progression through transferring miR-34a-devoid exosomes to cancer cells, and, mechanistically, the miR-34a-5p/AXL axis induces EMT via the AKT/GSK-3β/β-catenin signaling pathway." (PMID 33763422, 2021). "Although the proteome profile assay showed favorable results by modulating Decorin and M-CSF proteins, our analysis also demonstrates an up-regulation of the cancer-related proteins AXL, CEACAM-5, and SNAIL due to the effect of the drugs." (PMID 34641286, 2021). "In cancer cells, the activation of AXL signaling stimulates cell survival and increases migratory and invasive potential." (PMID 34638349, 2021). "Rationale: The type I insulin-like growth factor receptor (IGF-1R) signaling pathway plays key roles in the development and progression of numerous types of human cancers, and Src and AXL have been found to confer resistance to anti-IGF-1R therapies." (PMID 33408789, 2021). "After confirmation that NB4 is resistant to ATRA and it is known that AXL-RTK provides resistance in various cancers, therefore we first looked for the expression of AXL-RTK in sensitive and resistance NB4 cells through real-time PCR." (PMID 34140003, 2021). "Prostate CSCs expressed high levels of GAS6, suggesting that MERTK and/or AXL functions in cancer stem cells are related to their kinase activity." (PMID 34830794, 2021). "By terminating TLR signaling in dendritic cells and suppressing NK, AXL generates an immunosuppressive environment and helps cancer cells to evade immune surveillance." (PMID 34638349, 2021). "In providing effective cancer chemotherapy, it is better co-administer a AXL blocker such as BGB324 with CP and pemetrexed." (PMID 33921908, 2021). "Currently, ongoing clinical trials have been aimed at identifying combinatorial therapeutic schemes which include AXL inhibition and are optimal for particular cancer types." (PMID 34638349, 2021). "Reduced histone acetylation of the AXL promoter led to the upregulation of AXL expression that correlated with therapy resistance and adverse prognosis in some types of cancers." (PMID 34497683, 2021). "Overexpression of AXL has been reported in a multitude of tumors, which makes it an attractive target for cancer therapy." (PMID 34203870, 2021). "Particularly, AXL, a key receptor tyrosine kinase that confers resistance against targets and chemotherapeutics, is highly expressed in mesenchymal cancer cells." (PMID 33207077, 2021). "AXL is a member of the receptor tyrosine kinase family (RTKs), relating to the proliferation and invasion of cancer cells." (PMID 34203870, 2021). "Lymphoid lineage cells including T cells, B-cells, and NK cells are increased when pharmacologic and genetic inhibitions of AXL are treated to cancer cells." (PMID 34778071, 2021). "AXL is a receptor tyrosine kinase expressed in different types of cancer and in relation to resistance against various anticancer therapeutics due to poor clinical prognosis." (PMID 34778071, 2021). "For example, one previous study showed that the decreased shedding of AXL (and other RTKs) in cancer cells under the stress of Mitogen-activated protein kinase inhibitor (MEKi, U0126, and PD325901) resulted in cancer drug resistance." (PMID 33947097, 2021).